FOSB (FosB proto-oncogene, AP-1 transcription factor subunit)
Diseases named in the same sentence as FOSB in open-access papers (continued):
Sharing a sentence is not in itself a finding about the gene and the disease.
liver cancer (4 papers, 2018 to 2024). An epithelial or non-epithelial malignant neoplasm that arises from the liver. "expanded on this intricate relationship, suggesting a mechanism where interferon-a inhibits HIF1a signaling in liver cancer cells by suppressing FosB transcription." (PMID 37817774, 2023). "As a result, only the FOSB and SPP1 genes are suitable for use as prognostic biomarkers of liver cancer, where the FOSB is a low-risk gene while the SPP1 is a high-risk gene." (PMID 34238253, 2021). "Among these, the expression levels of ESR1,SPP1 and FOSB genes were closely related to the survival time of liver cancer patients." (PMID 34238253, 2021). "The results showed that among these Hub Genes, the expression levels of ESR1, SPP1 and FOSB genes was closely related to the survival time of liver cancer patients, with statistically significant differences (p < 0.05)." (PMID 34238253, 2021). "In other words, the survival rate of liver cancer patients with high expression of FOSB is higher than that of patients with low expression." (PMID 34238253, 2021). "The liver cancer survival rate was linked to ESR1, SPP1, and FOSB gene expression." (PMID 38726411, 2024). "Finally, single-gene GSEA analysis was performed on the three prognostic genes, ESR1, SPP1 and FOSB, that affect the survival time of liver cancer patients in order to explore the mechanism affecting the prognosis of liver cancer patients." (PMID 34238253, 2021).
metastatic disease (4 papers, 2007 to 2022). "Expression of the FOSB gene was associated with metastasis but the additional identification of associations between FOSB and 5 other genes having increased expression in the metastatic tumors resulted in the top ranking of FOSB and a "strong" heuristic label." (PMID 18088408, 2007). "Thus, the decrease of FOSB in metastatic disease may cause divergence between TNFα and IL-6 PCa expression levels by changing the available ratios of the corresponding translated proteins for dimerization." (PMID 36371231, 2022). "Nuclear FOSB was significantly increased in the metastatic tumors compared to the locally invasive tumors (p = 0.0013, two-tailed Mann Whitney test) thus confirming the association highlighted by Literature Lab." (PMID 18088408, 2007).
non-small cell lung carcinoma (4 papers, 2019 to 2025). A group of at least three distinct histological types of lung cancer, including non-small cell squamous cell carcinoma, adenocarcinoma, and large cell carcinoma. "FBJ Murine Osteosarcoma Viral Oncogene Homolog B (FOSB), a classic AP-1 family member, was previously reported to play bewilderingly two-polarized roles in non-small cell lung cancer (NSCLC) as an enigmatic double-edged sword, for which the reasons and significance warrant further elucidation." (PMID 39164746, 2024). "Bearing this in mind, it should come as no surprise that the FBJ Murine Osteosarcoma Viral Oncogene Homolog B (FOSB), a classical AP-1 transcription factor, has been reported to play two-sided roles in the progression and prognosis of non-small cell lung cancer (NSCLC)." (PMID 39164746, 2024).
ovarian carcinoma (4 papers, 2008 to 2025). A malignant neoplasm originating from the surface ovarian epithelium. "In studies of ovarian cancer, FOSB gene expression serves as a key prognostic indicator in patients undergoing treatment." (PMID 40508971, 2025). "Norepinephrine can induce ovarian cancer cells to produce IL-6 and IL-8 through effects on the Src protein and FosB protein, respectively, and thus promote angiogenesis in ovarian cancer." (PMID 34307378, 2021). "We analysed the expression of c-Fos, FosB, Fra-1 and Fra-2 to investigate the function of Fos transcription factors in ovarian cancer." (PMID 18854825, 2008). "This study investigated the potential function of Fos transcription factors in ovarian cancer and analysed the expression and prognostic significance of c-Fos, FosB, Fra-1 and Fra-2 in patients with invasive epithelial ovarian carcinoma." (PMID 18854825, 2008). "However, our results could not show an impact of Fra-1, Fra-2 and FosB on ovarian cancer progression." (PMID 18854825, 2008).
prostate carcinoma (4 papers, 2007 to 2025). A carcinoma that arises from epithelial cells of the prostate gland. "Immunohistochemistry subsequently confirmed increased nuclear FOSB staining in metastatic compared to locally invasive prostate cancers." (PMID 18088408, 2007). "The FOSB gene, which also participates in the TGF-β signalling pathway, is required for migration and invasion in prostate cancer cells." (PMID 40167331, 2025).
alcohol use disorder (3 papers, 2012 to 2023). "Alcohol increases the expression of FOSB in the mesocorticolimbic system, which is believed to contribute to alcohol use disorder." (PMID 36899881, 2023). "ΔFosB and FosB are members of the Fos family of transcription factors implicated in neural plasticity in drug addiction; a connection between electroacupuncture's treatment of alcohol abuse and the Fos family has not been established." (PMID 22792289, 2012). "In this study, we analyzed FosB mRNA expression in peripheral blood lymphocytes (PBLs) of patients with crack-cocaine and alcohol use disorders in comparison to non-addicted subjects." (PMID 30405417, 2018). "Socio-demographic characteristics and FosB expression values of the healthy non-user controls (CONT, n = 12) subjects, crack-cocaine use disorder (CUD, n = 10), and alcohol use disorder (AUD, n = 12) patients." (PMID 30405417, 2018).
Alzheimer disease (3 papers, 2022 to 2025). A progressive, neurodegenerative disease characterized by loss of function and death of nerve cells in several areas of the brain leading to loss of cognitive function such as memory and language. "Incidentally, specific transcription factors, such as Nr4a2 and FosB, have been implicated in the processing of odor information, with alterations in their expression correlating with early olfactory dysfunction in Alzheimer’s disease mouse models." (PMID 38892173, 2024).
asthma (3 papers, 2022 to 2024). "Prior research has found that patients with asthma show high expression levels of FosB and Egr3." (PMID 38666929, 2024). "In addition to POSTN (a known prognostic marker for asthma), FOSB can be observed to be upregulated in asthmatics." (PMID 35406434, 2022).
endometriosis (3 papers, 2020 to 2025). The growth of functional endometrial tissue in anatomic sites outside the uterine body. "Repeated genes from the MS-phase (CCN1, CRISP3, EGR1, FOS, FOSB, and TRPM6) could be associated with affected receptivity in endometriosis." (PMID 32474803, 2020). "In endometriosis, JUNB collaborates with AP-1 members (e.g., FOS, FOSB) to drive early-stage M1 polarization and inflammation, mirroring our findings in denervated muscle." (PMID 40917776, 2025).
epithelioid hemangioendothelioma (3 papers, 2016 to 2024). A low-grade malignant blood vessel neoplasm. "We examined FOSB immunohistochemistry (IHC) in 27 cases consisting of 4 PHE and its histologic mimics including 6 epithelioid hemangioendotheliomas (EHE), 8 angiosarcomas (AS), 4 Kaposi sarcomas (KS) and 5 epithelioid sarcomas (ES)." (PMID 27515856, 2016).
gastric cancer (3 papers, 2020 to 2025). A primary or metastatic malignant neoplasm involving the stomach. "On the contrary, overexpression of FOSB has repressed cell proliferation and migration in gastric cancer." (PMID 41272900, 2025). "Similarly, in gastric cancer, abnormal FOSB expression correlates with tumor progression and poor survival; more precisely, the overexpression of FOSB suppresses cell proliferation, clone formation, and migration, while the down-regulation of FOSB promotes these processes." (PMID 40361912, 2025).
Hypertension (3 papers, 2018 to 2024). The presence of chronic increased pressure in the systemic arterial system. "Not only is Ace1 upregulated following CIH, but inhibition of ACE1 prevents CIH-mediated increases in MnPO FosB and hypertension." (PMID 39133776, 2024). "Male mice displayed an elevation in the number of FOSB/ΔFOSB-positive cells in brainstem structures previously reported to be involved in CIH-induced hypertension in male rats, i.e., the SolC and the rVLM." (PMID 29988603, 2018).
lung adenocarcinoma (3 papers, 2017 to 2024). A carcinoma that arises from the lung and is characterized by the presence of malignant glandular epithelial cells. "To further explore this phenomenon, we analysed the expression of EINCR1 and two EGF-inducible genes, FOS and FOSB across the lung adenocarcinoma samples in the TCGA-LUAD dataset." (PMID 28732076, 2017).
lymph node metastasis (3 papers, 2012 to 2022). "The FOSB promoter SNP (rs12373539) may be associated with lymph node metastasis of PTC." (PMID 23181129, 2012). "In addition, FOS and FOSB were downregulated when lymph node metastasis was present, while CD27 and SELL were upregulated." (PMID 35037412, 2022).
Obesity (3 papers, 2012 to 2022). Accumulation of substantial excess body fat. "These factors, which include Rb, Maf, fosB, Taz, and Ebf1, have been the subjects of intense inquiry given obvious links to two human diseases of great importance, osteoporosis and obesity." (PMID 23209378, 2012). "Furthermore, at T3, we observed reduced expression of key transcription factors NFKB1, FOSB, NCOR, CIITA with pregravid obesity (2-4 fold drop in leans vs. 4-6 fold drop in obese)." (PMID 34195568, 2021).
psoriasis (3 papers, 2021 to 2022). An autoimmune condition characterized by red, well-delineated plaques with silvery scales that are usually on the extensor surfaces and scalp. "Taken together, loss of N4BP1 results in not only abnormal keratinocyte proliferation but also abnormal neutrophil maturation and infiltration by directly controlling JunB, FosB, and CXCL1, respectively, leading to susceptibility to psoriasis." (PMID 33990547, 2021). "AP-1 transcription factor superfamily (including JUN, JUNB, JUND, FOS, FOSB, FRA1, and FRA2) is essential in the pathogenesis of psoriasis." (PMID 35075118, 2022). "Together with induction of AP1 members FOSB, FOSL1, JUN and JUNB, and EGR signalling, our data identify regulatory pathways induced by 311 nm UVB in psoriasis that control terminal differentiation of keratinocytes." (PMID 33812333, 2021). "Here, we unraveled another member that is N4BP1, plays critical role both in keratinocytes and neutrophils by directly controlling mRNA stability of several key genes including JunB, FosB, and CXCL1, and through such mechanism maintains skin hemostasis to prevent the development of psoriasis." (PMID 33990547, 2021).
Sepsis (3 papers, 2013 to 2024). Sepsis is defined as life-threatening organ dysfunction caused by a dysregulated host response to infection. "Among the upregulated DEGs in E-SEP compared to Y-SEP, we observed inflammation-associated genes, such as FOSB, DUSP1, and JUNB, and aging-associated genes, such as IFN-stimulated genes DDIT4 and DUSP2, thereby indicating an overactive inflammatory response of cDCs in elderly patients with sepsis." (PMID 38909272, 2024).
status epilepticus (3 papers, 2016 to 2017). Status epilepticus is defined as a continuous seizure lasting more than 30 min, or two or more seizures without full recovery of consciousness between any of them. "Kainic acid induces recurrent seizures, and the selected time point (i.e., 6 h) after the induction of status epilepticus enabled us to observe not only late-response genes but also early-response genes (e.g., Fos, JunB, FosB, Egr2, Egr4)." (PMID 25636686, 2016). "In our previous experiments, we used an antibody against FosB/ΔFosB chosen on the basis of the transient induction of immunoreactivity observed after exposure to status epilepticus, as well as for the subsequent reappearance of immunoreactivity for FosB/ΔFosB in epileptic rats." (PMID 28018175, 2016). "Real-time PCR analysis showed the expected higher levels of Arc, FosB, Inhba, Npas4, Pchd8 and Tll1 bound to Upf1 after status epilepticus whereas levels of Slc1a2 were not different between groups." (PMID 28128343, 2017).
breast tumor (2 papers, 2013 to 2016). "We have shown that the level of FOSB is significantly decreased in grade II/III TNBC samples (moderately differentiated or poorly differentiated tumor); this is in agreement with previous reports of strong FOSB expression in normal breast epithelia or well-differentiated breast tumor." (PMID 27248170, 2016).
cardiomyopathy (2 papers, 2024 to 2025). A disease of the heart muscle or myocardium proper. "Hence, it is plausible that the release of TFs FOS, FOSB, and JUNB by C6 S100A4+ SMCs contributes to exacerbating cardiomyopathies, potentially through the induction of cardiac fibrosis and inflammation." (PMID 40717095, 2025). "The transcription factors FOS, FOSB, and JUNB may help prevent adverse events such as cardiac fibrosis in cardiomyopathy." (PMID 40717095, 2025). "Based on the findings of cell type-specific regulatory activity, the most active TFs in each of the 4 cardiomyopathy fibroblast subpopulations, including NR3C1 (C0 THBS4+ Fibroblasts), KLF4 (C1 LINC01133+ Fibroblasts), FOSB (C2 FGF7+ Fibroblasts), FOS (C3 AGT + Fibroblasts)." (PMID 38799173, 2024).
cervical cancer (2 papers, 2017 to 2020). A primary or metastatic malignant neoplasm involving the cervix. "FOSB expression is also significantly higher in cervical cancer compared to normal cervix; therefore, it may be a potential target to help overcome immune suppression." (PMID 28670312, 2017). "We found that HPV E6/E7-related master regulators (ENO1, FOSB, PA2G4, SOX9, TEAD4, FOXO4, and MNT) were significantly differently expressed (p < 0.001) in the cervical cancer TCGA samples (n = 306) than in normal cervix (n = 11) tissue." (PMID 28670312, 2017). "The following genes ENO1, FOSB, PA2G4, SOX9, and TEAD4 were highly expressed in cervical cancer in comparison to normal cervix (p < 0.001), while FOXO4 and MNT were significantly lower in cervical cancer (p < 0.001)." (PMID 28670312, 2017).
cocaine abuse (2 papers, 2010 to 2016). Disorders related or resulting from use of cocaine. "Based on our MiSearch publications search, we find that both FOS and FOSB are well established as candidate genes for both lithium response and cocaine abuse." (PMID 21092101, 2010). "Notably, the keyword "forebrain" characterizing the interaction between FOS and FOSB is also consistent with cocaine abuse." (PMID 21092101, 2010).
heart failure (2 papers, 2023 to 2024). Inability of the heart to pump blood at an adequate rate to meet tissue metabolic requirements. "Second, we identified EGR1, EGR2, FOS and FOSB as potential diagnostic biomarkers and therapeutic targets for heart failure." (PMID 36859608, 2023). "Through PPI network and logistic regression, we identified EGR1, EGR2, FOS and FOSB as potential diagnostic biomarkers and therapeutic targets for heart failure." (PMID 36859608, 2023). "In addition, we identified EGR1, EGR2, FOS and FOSB as potential diagnostic biomarkers and therapeutic targets for heart failure." (PMID 36859608, 2023).
hepatocellular carcinoma (2 papers, 2019 to 2024). A malignant tumor that arises from hepatocytes. "Furthermore, the transcriptional activation of MMP7 by the FOSB-MAFG transcription factor complex was demonstrated to be critical for the malignant progression in hepatocellular carcinoma." (PMID 39164746, 2024).
idiopathic pulmonary fibrosis (2 papers, 2021 to 2023). Idiopathic pulmonary fibrosis (IPF) is a nonneoplastic pulmonary disease that is characterized by the formation of scar tissue within the lungs in the absence of any known cause. "The localisation of the NK1-R distribution associated with that of FOSB/ΔFOSB-positive cells suggested that neurons of the Pre-Bötzinger complex, the inspiratory rhythm generator, displayed a long-term modification of their activity following an experimental induction of pulmonary fibrosis." (PMID 37383147, 2023). "The pulmonary fibrosis-induced neuronal plasticity at the respiratory network level was evaluated through immunodetection of the long-term neuronal markers FOSB/ΔFOSB." (PMID 37383147, 2023).
mesothelioma (2 papers, 2008 to 2023). A usually malignant and aggressive neoplasm of the mesothelium which is often associated with exposure to asbestos. "Among the Mesothelioma-specific hits we observed YREs in the loci of three MAPK-responsive TFs: JUN, FOSL1 and FOSB." (PMID 37400441, 2023).
Miscarriage (2 papers, 2017 to 2025). A pregnancy that ends at a stage in which the fetus is incapable of surviving on its own, defined as the spontaneous loss of a fetus before the 22th week of pregnancy. "Three significant genes – FOS, FOSB, and LY96 – associated with miscarriage were identified; these genes are up-regulated during infection but suppressed by the vaccine." (PMID 41232126, 2025). "Further research on 17 core enriched genes expressed at the MFI indicated that CXCL11, MMP10, FOS, FOSB, LY96, and NCF2 may be closely related to miscarriage." (PMID 41232126, 2025).
neuroblastoma (2 papers, 2020 to 2025). Neuroblastoma (NB) is the most common solid, extracranial childhood tumor. "Using CRISPR, we developed and screened guide RNAs (gRNA) specific to the FosB gene, which encodes ΔFosB, and tested these in cultured mouse neuroblastoma (Neuro2A) cells." (PMID 32901027, 2020).
neuropathic pain (2 papers, 2019 to 2023). Chronic pain caused by damage to nerve fibers. "We investigated the effects of voluntary running (VR) on FosB+ cells and GABAergic interneurons (parvalbumin-positive [PV+] and somatostatin-positive [SOM+]) in the vHPC-CA1 in neuropathic pain (NPP) model mice." (PMID 36788313, 2023).
schizophrenia (2 papers, 2018 to 2019). A major psychotic disorder characterized by abnormalities in the perception or expression of reality. "FOS and FOSB, which are implicated in the amphetamine addiction pathway, were up-regulated in schizophrenia fibroblast samples." (PMID 30967896, 2019). "Two genes in the FOS family (FOS and FOSB) were up-regulated in schizophrenia samples." (PMID 30967896, 2019). "The analysis of the top 10 DEGs in schizophrenia and healthy samples revealed that FOS and FOSB (which are involved in the AMPH addiction pathway), were significantly up-regulated in schizophrenia fibroblast samples." (PMID 30967896, 2019). "A previous study of GEO datasets GSE62333 also reported the up-regulation of FOSB and FOS in the fibroblasts of schizophrenia patients and mainly focused on EGR1 and other genes as biomarkers for disease diagnosis." (PMID 30967896, 2019).
Stroke (2 papers, 2014 to 2025). Sudden impairment of blood flow to a part of the brain due to occlusion or rupture of an artery to the brain. "We observed that rehabilitation significantly increased Zif268 expression in both types of neurons and FosB expression in the stroke-projecting neurons." (PMID 40089466, 2025).
abdominal aortic aneurysm (1 paper, 2025). Enlargement and ballooning of the vessel that supplies arterial blood to the abdomen, pelvis and legs. "FOSB represents a promising potential therapeutic target for mitigating the progression of Abdominal Aortic Aneurysm." (PMID 40486911, 2025). "Exosome-related gene FOSB was involved in the progression of abdominal aortic aneurysm." (PMID 40486911, 2025). "FOSB expression in vascular smooth muscle cells (VSMCs) influences their phenotypic transformation, promoting MMP2/MMP9 expression, potentially accelerating abdominal aortic aneurysm (AAA) development." (PMID 40486911, 2025).